CAT (catalase)
Diseases named in the same sentence as CAT in open-access papers (continued):
Sharing a sentence is not in itself a finding about the gene and the disease.
renal cell carcinoma (3 papers, 2009 to 2024). "In contrast, the catalase and SOD levels in the in-remission WT, hypernephroma, and CCS pediatric patients’ groups were significantly increased after one year of chemotherapy compared to their levels before treatment." (PMID 39334568, 2024). "Furthermore, after one year of chemotherapy, the catalase and SOD levels in relapsed WT and hypernephroma pediatric patients were significantly decreased compared to their levels before treatment." (PMID 39334568, 2024).
sarcoma (3 papers, 2011 to 2019). A usually aggressive malignant neoplasm of the soft tissue or bone. "Catalase activity was decreased in sarcoma patients by 43% in comparison to the control value." (PMID 21871117, 2011). "Transfer to suspension cultures led to rapid formation of sarcoma spheroids, as described 40; this dramatically increased ROS levels, which was reversed by NAC or catalase antioxidants (Fig EV1E)." (PMID 31668005, 2019). "Level of liver MDA was markedly increased, whereas activities of liver SOD, CAT, GSH-Px and GR were significantly reduced in mice implanted with S180 sarcoma (group III)." (PMID 22754316, 2012). "To summarise, our studies for the first time on oxidative stress and antioxidant status in both sarcomas clearly indicated an increase in oxidative stress (enhanced lipid and protein damage) and decrease in antioxidant status (lowered SOD, CAT, thiols, TEAC)." (PMID 21871117, 2011). "The non-enzymatic antioxidant status (TEAC and total SH) as well as the enzymatic antioxidant status (CAT and SOD) was observed to have significantly decreased in the sarcoma patients." (PMID 21871117, 2011). "Mice implanted with S180 sarcoma showed a significant increase in serum AST, ALT and ALP activities, liver MDA level, decrease in serum WBC, TP, ALB, A/G, TNF-α and IFN-γ, and liver GSH, SOD, CAT, GSH-Px and GR activities." (PMID 22754316, 2012). "Sarcoma patients showed significant increase in plasma and urinary MDA and serum protein carbonyl levels (p < 0.05) while significant decreases were noted in TEAC, thiols, CAT and SOD levels (p < 0.05)." (PMID 21871117, 2011). "It was evident that the antioxidant enzymes (SOD and CAT) and non-enzymes (thiols and TEAC) measured in this study were significantly lowered in sarcoma patients compared to healthy individuals." (PMID 21871117, 2011). "The antioxidant status based on the levels of enzymatic antioxidants (SOD and CAT) and non-enzymatic antioxidants (TEAC and thiols) in both sarcomas were compared." (PMID 21871117, 2011).
Seizure (3 papers, 2019 to 2025). A seizure is an intermittent abnormality of nervous system physiology characterized by a transient occurrence of signs and/or symptoms due to abnormal excessive or synchronous neuronal activity in the brain. "Seizures are often preceded by abnormally low SOD and CAT levels." (PMID 37539232, 2023).
selenium deficiency (3 papers, 2017 to 2025). A nutritional deficiency disease resulting from inadequate selenium levels in the body, which can lead to impaired function of selenoproteins essential for antioxidant defense and thyroid hormone metabolism. "Selenium deficiency, or combined iodine and selenium deficiency, can cause significant alterations in the activities of antioxidant enzymes such as GPx, SOD, and CAT in the thyroid, liver, brain, kidneys, and plasma of rats." (PMID 28638832, 2017). "Selenium deficiency increases oxidative stress and increases inflammatory marker expression (iNOS, IL-1β, IL-12, IL10, PTGE, and NF-κB) and reduces the synthesis of antioxidant enzymes (CAT, T-AOC, SOD, and GSH-Px) in macrophages in vitro." (PMID 40681871, 2025). "Interestingly, a correlation with selenium deficiency has been evidenced, and supplementation of this element increased SOD and CAT activities." (PMID 38275651, 2024).
thrombosis (3 papers, 2012 to 2025). "We have found no studies related to association of GSH-Px and catalase enzyme activities with venous thrombosis." (PMID 24818025, 2014). "Treatment of HF-fed mice with a SOD mimetic or MitoQ, or genetic overexpression of catalase within mitochondria, not only lowered mitochondrial oxidants, hyperpolarization, Ca2+ levels, and platelet activation but also protected against increased potential for carotid and pulmonary thrombosis." (PMID 41433113, 2025).
toxoplasmosis (3 papers, 2019 to 2025). A parasitic disease contracted by the ingestion or fetal transmission of toxoplasma gondii. "Decreased CAT activity was also found in skin leishmaniasis and toxoplasmosis." (PMID 32143731, 2020). "Decreased levels of A0A0G2JIW1 (HSPA1B) and A0A384P5Q0 (catalase) along with enriched KEGG pathways including “longevity regulating pathway - multiple species,” “influenza A,” “glyoxylate and dicarboxylate metabolism,” and “toxoplasmosis” suggest vulnerabilities to aging and oxidative stress." (PMID 39562369, 2025).
Ureteral obstruction (3 papers, 2016 to 2025). Obstruction of the flow of urine through the ureter. "Similarly, CAT deficiency, as observed in a mouse model of unilateral ureteral obstruction, worsens tubulointerstitial fibrosis and elevates lipid peroxidation products that further contribute to tubulointerstitial injury." (PMID 41301558, 2025).
Ventricular arrhythmia (3 papers, 2021 to 2024). "Additionally, Ad.CAT not only reduced the susceptibility to ventricular arrhythmias, but also suppressed MI-evoked lethal ventricular arrhythmias such as VT/VF in T2DM." (PMID 35548411, 2022). "Additionally, Ad.CAT gene transfection also restored the heterogeneity of ventricular electrical activities, reduced the susceptibility to ventricular arrhythmias, and suppressed acute MI-evoked ventricular arrhythmias in T2DM rats." (PMID 35548411, 2022). "In vivo Ad.CAT gene transfection into CVP neurons markedly improved the heterogeneity of ventricular electrical activity, reduced the susceptibility to ventricular arrhythmias, and suppressed MI-evoked ventricular arrhythmias in T2DM rats." (PMID 35548411, 2022). "Consequently, Ad.CAT gene transfection improved the cardiac vagal function, alleviated the heterogeneity of ventricular electrical activity, and suppressed MI-evoked ventricular arrhythmias in T2DM rats." (PMID 35548411, 2022). "Ad.CAT gene transfection into CVP neurons failed to induce the significant reduction in the incidence of VT/VF, but it significantly reduced the susceptibility to ventricular arrhythmias (0.38 ± 0.26 for the inducibility quotient) in T2DM rats." (PMID 35548411, 2022).
vitamin A deficiency (3 papers, 2018 to 2022). Deficiency of vitamin A due to malnutrition, malabsorption, or dietary lack. "Notably, vitamin A deficiency itself enhances oxidative stress, as indicated by the changes in the activity of catalase, glutathione-S-transferase, glutathione peroxidase, DT diaphorase and urate oxidase in the livers of vitamin A-deficient rats and mice." (PMID 29892071, 2018). "Meanwhile, it was demonstrated that CAT and GSH-Px expression in the brain tissue were altered endogenously in the rat hippocampus affected by nutritional vitamin A deficiency, which can impair the temporal orchestration of hippocampal daily cognitive performance." (PMID 35757215, 2022). "Vitamin A deficiency leads to lower GSH/GSSG ratio in rat liver, less activity of glutathione-S-transferase in lung, and less lung SOD and catalase." (PMID 30150942, 2018).
vitamin D deficiency (3 papers, 2023 to 2025). A nutritional condition produced by a deficiency of VITAMIN D in the diet, insufficient production of vitamin D in the skin, inadequate absorption of vitamin D from the diet, or abnormal conversion of vitamin D to its bioactive metabolites. "NMSC patients with vitamin D deficiency presented lower catalase activity levels in erythrocytes, and the highest values of CARBS, while control patients with vitamin D sufficiency presented the lowest values of TBARS." (PMID 37237973, 2023). "Vitamin D deficiency led to an increase in activities of the glutathione-dependent enzymes and a decrease in SOD and catalase enzymes in rat muscle." (PMID 36901794, 2023). "As was discussed in an earlier part of the present study, we assumed that vitamin D deficiency increased oxidative stress, thereby leading to increased SOD, CAT, and GPx activity; furthermore, vitamin D3 supplementation improved oxidative damage and the balance of the antioxidant system." (PMID 39758177, 2025). "NMSC patients diagnosed with SCC showed lower catalase activity values compared to non-cancer patients (p < 0.001), with the lowest values occurring in patients with a chronic cancer diagnosis (p < 0.001) and vitamin D deficiency (p < 0.001)." (PMID 37237973, 2023).
vitamin deficiency (3 papers, 2019 to 2024). A disorder that is caused by the deficiency of a vitamin. "Regarding the first: endothelial damage results from the combination of excessive ROS/RNS production and inadequate antioxidant systems (decreased SOD and catalase activity, reduced glutathione (GSH) accumulation, and potential vitamin deficiencies))." (PMID 38474158, 2024).
acute alcoholic hepatitis (2 papers, 2021). "Serum CAT activity moderately increases in fatty liver and acute alcoholic hepatitis." (PMID 34768813, 2021). "The serum CAT activity was moderately increased in fatty liver and acute alcoholic hepatitis." (PMID 33808318, 2021).
acute coronary syndrome (2 papers, 2019 to 2022). Signs and symptoms related to acute ischemia of the myocardium secondary to coronary artery disease. "Similarly, interval cycloergometer CR training, five times a week, for a total of 15 training sessions increased TAS, SOD-1, and glutathione peroxidase (GPx) activity in acute coronary syndrome patients, but decreased CAT activity." (PMID 31003426, 2019).
acute lung injury (2 papers, 2021 to 2023). A condition of lung damage that is characterized by bilateral pulmonary infiltrates (pulmonary edema) rich in neutrophils, and in the absence of clinical heart failure. "Furthermore, it has been reported that the PO extract could elevate the SOD and CAT levels, while downregulating the MDA level in lipopolysaccharide- (LPS-) induced acute lung injury rats." (PMID 34381307, 2021).
Age-related cataract (2 papers, 2022 to 2024). A type of cataract (opacification of the lens) that forms during the course of aging. "Both superoxide dismutase and catalase have been implicated in age-related cataracts, emphasizing the importance of this pathway for lens homeostasis, even though levels of superoxide dismutase 1, the cytoplasmic form implicated in age-related cataracts, is relatively low in the lens." (PMID 39594457, 2024). "In addition, the SOD, CAT, and GPx content in the lenses of senile cataracts have decreased significantly with increasing lenticular nucleus hardness grading." (PMID 35163178, 2022). "Examination of the serum CAT and SOD levels can be an important quantitative indicator for the clinical diagnosis of senile cataracts." (PMID 35163178, 2022).
airway hyperresponsiveness (2 papers, 2020). "Airway hyperresponsiveness, cell count, cytokine levels in BAL fluid, lung histopathology, IgE levels, and oxidative stress indices including plasma level of MDA, pulmonary antioxidant enzymes (SOD and CAT) levels, HP content, and collagen fiber accumulation in lung tissue were measured." (PMID 33162970, 2020).
alcoholic liver damage (2 papers, 2016 to 2025). "Past studies have reported that alcoholic liver damage induces the expression of SOD, catalase and GPx." (PMID 27809254, 2016).
allergies (2 papers, 2018 to 2022). "It is found that there are 50 potential targets of PLP in allergy, which were imported into the String database to establish PPI, among which the top 5 interaction relationships according to the number are: INS, TNF, CAT, MAPK1 and VEGFA." (PMID 35879791, 2022).
amnesia (2 papers, 2020). Pathologic partial or complete loss of the ability to recall past experiences ( AMNESIA, RETROGRADE) or to form new memories ( AMNESIA, ANTEROGRADE). "As another natural phenol, phloretin improved the amnesia induced by scopolamine in mice via enhancing the activity of antioxidant enzymes, especially CAT, and SOD, and decreasing the level of MDA which all are in near interconnection with Nrf2." (PMID 33114450, 2020). "As another alkaloid, embelin (2,5-dihydroxy-3-undecyl-1,4-benzoquinone) notably improved the memory retention and recognition index in scopolamine-induced amnesia in rats by elevated expression of SOD1 and CAT as Nrf2 target genes." (PMID 33114450, 2020).
anxiety disorder (2 papers, 2013 to 2022). A category of psychiatric disorders which are characterized by anxious feelings or fear often accompanied by physical symptoms associated with anxiety. "Further, studies in populations with anxiety disorders have demonstrated increased activity of antioxidant enzymes superoxide dismutase (SOD), catalase (CAT), xanthine oxidase, glutathione reductase (GSR), and glutathione peroxidase." (PMID 23785661, 2013). "In comparison to healthy controls, individuals with anxiety disorders were reported to show increased levels of oxidative stress indicators such as glutathione peroxidase, superoxide dismutase (SOD), catalase (CAT), and malondialdehyde (MDA) in their blood samples." (PMID 36499240, 2022).
asbestosis (2 papers, 2013 to 2022). A lung disorder caused by inhalation of asbestos fibers. "Analysing the interactions between different genotypes, the association between MnSOD Ala –9Val polymorphism and the risk of asbestosis was modified strongly by CAT –262 C > T polymorphism." (PMID 23984360, 2013). "The associations between MnSOD Ala −9Val polymorphism and the risk of asbestosis and between iNOS genotypes and asbestosis were modified by CAT –262 C > T polymorphism (P = 0.038; P = 0.031)." (PMID 23984360, 2013). "The CAT −262 TT and combined CAT CT and CC genotypes showed a very different magnitude of association between the cumulative asbestos exposure and risk of asbestosis." (PMID 23984360, 2013). "A crucial finding of the current study shows that CAT –262 C > T polymorphism strongly modifies the association between MnSOD Ala –9Val polymorphism and the risk of asbestosis." (PMID 23984360, 2013). "The study comprised 262 cases with asbestosis and 265 controls with no asbestos-related disease previously studied for MnSOD, ECSOD, CAT, GSTT1, GSTM1, GSTP1, and iNOS polymorphisms." (PMID 23984360, 2013).
atopic dermatitis (2 papers, 2015 to 2025). "Control immune response, transepidermal water loss, and sebum concentration in dogs with atopic dermatitis.Antioxidant action by increasing serum superoxide dismutase and catalase levels." (PMID 40732081, 2025).
beta thalassemia (2 papers, 2012 to 2015). Beta-thalassemia (BT) is characterized by deficiency (Beta+) or absence (Beta0) of synthesis of the beta globin chains of hemoglobin (Hb). "Studies published on the status of antioxidant enzymes like catalase, superoxide dismutase, glutathione, and glutathione S-transferase in beta thalassemia patients also showed variable results." (PMID 22645668, 2012). "A study revealed increased levels of antioxidant enzymes superoxide dismutase, catalase, and glutathione peroxidase in red blood cells of beta thalassemia minor and near normal values of these enzymes in red blood cells of beta thalassemia major patients." (PMID 22645668, 2012).
bronchiectasis (2 papers, 2019 to 2021). Segmental, irreversible dilation of the bronchial tree resulting in the accumulation of secretions which leads to obstruction. "The present study showed that compared to healthy controls, adults with bronchiectasis who were clinically stable presented increased levels of IL-6, IL-10, carbonylated proteins, and superoxide anion, and decreased catalase activity." (PMID 33886789, 2021). "In the present study, we observed an increased level of catalase activity in adults with bronchiectasis, possibly indicating a decreased rate of cellular degradation of this enzyme." (PMID 33886789, 2021). "Additionally, catalase activity correlated with the functional capacity and with the total number of steps walked in adults with bronchiectasis." (PMID 33886789, 2021). "A previous study reported that serum catalase activity and the levels of lipid peroxides (i.e., 2-thiobarbituric acid reactive substances and 8-isoprostanes) – which are markers of oxidative stress in the serum of patients with bronchiectasis – were significantly increased." (PMID 31844710, 2019). "The authors found higher levels of catalase, TAC, and TBARS in the bronchiectasis group than in the control group." (PMID 33886789, 2021).
Cachexia (2 papers, 2017 to 2023). Severe weight loss, wasting of muscle, loss of appetite, and general debility related to a chronic disease. "In a previous study, creatine supplementation attenuated cachexia and wasting-associated muscle loss, and in another, atenolol significantly suppressed immobilized-induced reductions in GSH, SOD, and catalase levels and increased MDA levels." (PMID 37238940, 2023). "Collectively, these findings suggest that increased protein levels of SOD and catalase were induced probably to offset the deleterious effects of ROS in limb muscles of the cancer-cachexia rats." (PMID 29255650, 2017). "Catalase protein content significantly increased in limb muscles of cancer-cachexia rats compared to non-cachexia controls." (PMID 29255650, 2017). "In cancer-cachexia rats, treatment with formoterol did not significantly modify protein SOD1, SOD2, or catalase levels in either diaphragm or gastrocnemius muscles." (PMID 29255650, 2017).
Candida infections (2 papers, 2017 to 2022). "Taken together, the findings offer a novel catalase‐photoinactivation approach to address multidrug‐resistant Candida infections." (PMID 35119220, 2022). "However, we find that catalase inactivation does not attenuate C. albicans virulence in mouse or invertebrate models of systemic candidiasis." (PMID 28542620, 2017).
Carbohydrate Metabolism Disorders (2 papers, 2021 to 2025). "Inherited deficiency of catalase (CAT) is associated with an increased risk of carbohydrate metabolism disorders and liver steatosis." (PMID 35052583, 2021).
celiac disease (2 papers, 2020 to 2025). An autoimmune genetic disorder with an unknown pattern of inheritance that primarily affects the digestive tract. "In the p31‐43 peptide‐induced celiac disease Caco‐2 cell model, PCNL‐FD significantly reduced oxidative stress by decreasing ROS and MDA levels while increasing GSH levels and antioxidant enzyme activities (SOD and CAT)." (PMID 41019173, 2025). "Myeloperoxidase (MPO) activity, adenosine deaminase, nitric oxide (NOx), thiobarbituric acid, catalase (CAT), superoxide dismutase (SOD), glutathione peroxidase (GPx), and DNA damage were evaluated in peripheral blood samples from 47 celiac disease patients and 31 controls." (PMID 32555942, 2020).